PRB1 (proline rich protein BstNI subfamily 1)
Synonyms: PM; PMF; PMS; PRB1M; PRB1L
Gene: Protein-coding gene on chromosome 12 (11,351,823 to 11,355,591, reverse strand). Ensembl gene ENSG00000251655.
Subcellular location: Secreted
Genetic constraint (gnomAD): Loss-of-function variants: 16 observed, 14.27 expected, observed/expected ratio (o/e) 1.12, 90% interval 0.76 to 1.68. The upper end of that interval is the gene's LOEUF score, 1.68, which puts it in group 6 of 6, group 1 being the genes least tolerant of losing a copy. Missense variants: 274 observed, 183.76 expected, observed/expected ratio (o/e) 1.49, 90% interval 1.35 to 1.65. Synonymous variants: 87 observed, 69.49 expected, observed/expected ratio (o/e) 1.25, 90% interval 1.05 to 1.5.
Homologues: Paralogues in human: PRB2 (83% identical), PRB3 (76% identical), PRB4 (76% identical), PRH1 (52% identical), PRH2 (46% identical), PRR4 (24% identical).
Diseases named in the same sentence as PRB1 in open-access papers:
PRB1 is named in the same sentence as 21 diseases in open-access papers, as found by Europe PMC text mining. Sharing a sentence is not in itself a finding about the gene and the disease. The quoted sentences say what the papers report.
breast carcinoma (2 papers, 2018 to 2024). "To further investigate the efficiency of A80.2HCl action on the MYC, KLHL42 and pRB1 axes identified in our study, we treated bladder cancer, prostate cancer and breast cancer cell lines with increasing doses of A80.2HCl." (PMID 38424044, 2024). "To test it, we measured the expression of RB1 and MYC in bladder, prostate and breast cancer cell lines and found that pRB1 protein levels were negatively correlated with MYC expression." (PMID 38424044, 2024).
gastric cancer (2 papers, 2015 to 2024). A primary or metastatic malignant neoplasm involving the stomach. "Interestingly, we showed that RB1 was more prone to phosphorylation in gastric cancer cells, and pRB1 was hardly expressed in fibroblasts." (PMID 38862740, 2024). "IHC assays of stomach cancer tissues also showed that RB1 and pRB1 were highly expressed in the tumour cells." (PMID 38862740, 2024).
retinoblastoma (2 papers, 2013 to 2024). A malignant tumor that originates in the nuclear layer of the retina. "Retinoblastoma results from RB1 gene inactivation and loss of pRB1, yet the proliferation and metastasis that underlie retinoblastoma development have not been well defined." (PMID 23559850, 2013).
asthma (1 paper, 2022). "The data suggest that PRB1 expression in induced sputum is increased in asthmatic subjects, which demonstrates its association with type 2‐high asthma." (PMID 35344278, 2022). "Our study suggests that proline‐rich protein BstNI subfamily 1 (PRB1) expression in induced sputum is increased in asthmatic subjects, which demonstrates its association with type 2‐high asthma." (PMID 35344278, 2022). "PRB1 protein levels in the induced sputum of 67 subjects with asthma and 27 controls were determined by an enzyme‐linked immunosorbent assay." (PMID 35344278, 2022). "We found that the area under ROC curve was equal to 0.7145, indicating PRB1 protein in induced sputum has diagnostic significance in asthma." (PMID 35344278, 2022). "The aim of this study is to reveal whether basic salivary proline‐rich protein BstNI subfamily 1 (PRB1) may be used as a diagnostic biomarker for type 2‐high asthma." (PMID 35344278, 2022). "Our study showed that the expression of PRB1 protein in induced sputum may have reliable diagnostic value for asthma, especially type 2‐high asthma." (PMID 35344278, 2022). "We then performed correlation analyses between PRB1 protein levels and various airway inflammation indicators, to determine the function of PRB1 in asthma further." (PMID 35344278, 2022). "PRB1 levels in induced sputum supernatant are helpful in the diagnosis of asthma and the AUC was 0.7145 (p = 0.0012)." (PMID 35344278, 2022). "We conducted ELISA to analyze the protein levels of PRB1 in the induced sputum supernatant to detect the expression of PRB1 in asthma and found that PRB1 is increased in the induced sputum of the asthmatic group (p = 0.0098)." (PMID 35344278, 2022). "To determine the relationship between PRB1 and type 2‐high asthma further, we detected the levels of IL‐2, IL‐4, IL‐5, IL‐6, IL‐10, IL‐13, IL‐17, and INF‐γ in the induced sputum supernatant." (PMID 35344278, 2022). "The expression of PRB1 in induced sputum is a potential biomarker for type 2‐high asthma." (PMID 35344278, 2022). "Therefore, we believe that PRB1 is a potential predictor of type 2‐high asthma." (PMID 35344278, 2022). "Second, we did not conduct research on the underlying mechanism of PRB1 in asthma." (PMID 35344278, 2022). "Thus, PRB1 may be a biological marker for type 2‐high asthma." (PMID 35344278, 2022). "Protein levels of PRB1 in induced sputum positively correlated with FENO, total serum IgE, EOS, and EOS% in peripheral blood, and these clinical indicators are biomarkers of type 2‐high asthma." (PMID 35344278, 2022). "Moreover, PRB1 has not been reported in asthma or other airway inflammatory diseases." (PMID 35344278, 2022).
bladder cancer (1 paper, 2024). "Moreover, data from mouse tumors and human bladder cancer tissues confirmed the repression of pRB1 protein abundance mediated by MYC and KLHL42." (PMID 38424044, 2024).
glioma (1 paper, 2022). A benign or malignant brain and spinal cord tumor that arises from glial cells (astrocytes, oligodendrocytes, ependymal cells). "We found that TRPML2 knock-down in glioma cells reduces total pRB1 as well as the active/hypophosphorylated form levels, compared with siGLO T98 and U251 cells." (PMID 35054871, 2022). "Then, the contribution of the proteasome in the TRPML2-dependent degradation of pRB1 protein in glioma cell lines was evaluated using CARF, a selective proteasome inhibitor." (PMID 35054871, 2022).
infertile (1 paper, 2024). "All OA-fertile men (n = 9) carried mutations in ZNF749 (sperm production), whereas OA-infertile men (n = 10) harbored mutations in PRB1, which is essential for DNA replication." (PMID 38403804, 2024).
ovarian carcinoma (1 paper, 2024). A malignant neoplasm originating from the surface ovarian epithelium. "In the current study, we have comprehensively investigated the sub-cellular localisation and clinicopathological significance of cyclins D1/E1, CDK2/4/6 and RB1/pRB1 in a cohort of clinical ovarian cancers." (PMID 38612869, 2024). "The CDK2/4/6, cyclin D1/E1 and RB1/pRB1 protein expression were investigated in 300 ovarian cancers and correlated with clinicopathological parameters and patient outcomes." (PMID 38612869, 2024). "To address this hypothesis, we have comprehensively evaluated the clinicopathological significance of the CDK2, CDK4, CDK6, cyclin D1, cyclin E1, RB1 and pRB1(Ser 795) protein expression in a clinical cohort of epithelial ovarian cancer." (PMID 38612869, 2024). "Cyclin-dependent kinases (CDK2, CDK4, CDK6), cyclin D1, cyclin E1 and phosphorylated retinoblastoma (pRB1) are key regulators of the G1/S cell cycle checkpoint and may influence platinum response in ovarian cancers." (PMID 38612869, 2024).
stomach cancer (1 paper, 2024). "Collectively, these results indicate that binding of KDM5B to pRB1 limits the transcriptional regulation of IL-8 expression in gastric tumour cells." (PMID 38862740, 2024). "Co-IP experiments showed that KDM5B could bind to pRB1 in gastric tumour cells." (PMID 38862740, 2024).
systemic lupus erythematosus (1 paper, 2021). An autoimmune multi-organ disease typically associated with vasculopathy and autoantibody production. "C3, CFH, SERPING1, FGA, and FGG were significantly enriched in the “complex and coagulation cascades pathway,” C3 was also enriched in the “systemic lupus erythematosus” pathway, and PRB1 in the “salivary secretion” pathway." (PMID 34516718, 2021).
tumor (12 papers, 2010 to 2024). "Moreover, the roles of E2F-1 in cancer have been well-recognized due to its association with pRB1— a classic tumor suppressor." (PMID 20976175, 2010). "RB is a tumor suppressing gene regulating survival, proliferation and differentiation in GBMs; moreover, a role of pRB1 in lysosome acidification, vesicle trafficking and autophagosome/lysosome fusion process has also been identified." (PMID 35054871, 2022). "This is intriguing since CagA likely blocks cell cycle progression by generating a dominant anti-proliferative response involving the canonical tumour suppressor genes, P21 and Retinoblastoma (pRB1)." (PMID 22312430, 2012). "The essential tumor suppressor Cdkn2a gene (Ink4a) is the main regulator of pRb1." (PMID 36234520, 2022). "The multivariate analysis included tumour stage and CDK4, CDK6, CDK2, cyclin D1, cyclin E1, RB1 and pRB1 protein expression." (PMID 38612869, 2024). "Four somatic variations (RP1L1, PRB1, HS6ST3 and DCTN1) were simultaneously occurred in both primary tumor and PM cancer." (PMID 26330360, 2015).
cancer (11 papers, 2010 to 2024). A tumor composed of atypical neoplastic, often pleomorphic cells that invade other tissues. "Our literature review revealed that except PRB1, all other candidate drivers have previously been associated with cancer immune infiltration, TME, and/or endoplasmic reticulum (ER) stress, thereby supporting their role as oncogenic drivers in IECs." (PMID 39456581, 2024). "Among them, the somatic mutation of RP1L1 and PRB1 caused gene activation with elevated mRNA expression in primary cancer, PM cancer or in both." (PMID 26330360, 2015). "Collectively, these results suggest that KLHL42 is a bona fide E3 ligase that modulates pRB1 protein ubiquitination and thus decreases pRB1 stability in cancers." (PMID 38424044, 2024). "Thus, our data suggest that high MYC expression drives resistance to CDK4/6i by reducing pRB1 protein abundance in cancer cells." (PMID 38424044, 2024). "Functional inactivation of pRB1 in various human cancers leads to deregulated E2F1 activity." (PMID 20976175, 2010). "Dysregulation of type D cyclins is a common event in cancer that contributes to tumorigenesis by promoting hyper-phosphorylation of pRB1 and activation of E2F target genes, which are important in promoting the transition of cells through early G1-phase to S-phase." (PMID 20930946, 2010). "We identify a compound that degrades MYC, A80.2HCl, which induces MYC degradation at nanomolar concentrations, restores pRB1 protein levels and re-establish sensitivity of MYC high-expressing cancer cells to CDK4/6i." (PMID 38424044, 2024). "High MYC expression activates the E3 ligase KLHL42, which is responsible for pRB1 ubiquitination and degradation and subsequently confers resistance to CDK4/6i to cancer cells." (PMID 38424044, 2024).
infection (3 papers, 2018 to 2023). The state of being infected such as from the introduction of a foreign agent such as serum, vaccine, antigenic substance or organism. "Analyzing the pathogenesis-related genes in DEGs of all samples, the internal factor leading to the changes might be pathogen infection and seven genes (PRB1, PR-1, E137, PER3, PER47, STH-2, NLTP) which were clustered together could be important to it." (PMID 34221719, 2021).
PRB1 also shares sentences with these, for which no sentence is quoted: myositis (2 papers); Azoospermia (1); bacterial vaginosis (1); chronic gastritis (1); colorectal cancer (1); inflammation (1); metastatic cancer (1); prostate carcinoma (1).